CCNB1 (cyclin B1)
Diseases named in the same sentence as CCNB1 in open-access papers (continued):
Sharing a sentence is not in itself a finding about the gene and the disease.
breast carcinoma (continued). "For example, Ki-67, STK15, Survivin, Cyclin B1, and MYBL2 have all been associated with breast cancer proliferation; Stromelysin 3 and Cathepsin L2 have been associated with invasion; and ER, PR, Bcl2, and SCUBE2 have been associated with responsiveness to Estrogen." (PMID 29848291, 2018). "They found that cyclin B1 expression was intimately affected by the efficiency of NF-κB translocation to the nucleus; moreover, ROS inactivation by MnSOD repressed cyclin B1 expression in human breast cancer cells." (PMID 30260967, 2018). "Higher levels of Ccnb1 are found in many cancers, especially breast cancer." (PMID 29795334, 2018). "The expression of cell cycle related proteins has been found to be higher in doxorubicin-resistant breast cancer cells and doxorubicin could induce prostate cancer apoptosis by inhibiting cyclin B1 expression." (PMID 30555632, 2018). "Here, our results demonstrate that SL4 was able to induce cell cycle arrest at the G2/M phase in breast cancer cells by activating the MAPK pathway and subsequently regulating cell cycle-associated proteins, including p21, cdc25C, cdc2, cyclin B1 and cyclin A2." (PMID 27819344, 2016). "Supporting the roles of ERLIN2 in stabilizing Cyclin B1 protein and enhancing Cyclin B1/Cdk1 function in breast cancer cells, levels of Cyclin B1 and phosphorylated Cdc27 were increased in ERLIN2-expressing MCF10A cells but decreased in ERLIN2-knockdown SUM225 cells, compared with their controls." (PMID 27462423, 2015). "The identified DEGs, which were involved in cell cycle, including CDC20, BUB1, GLIPR1, MCM2, and CCNB1, could have a crucial function in the development of breast cancer, and may become potential targets or prognostic markers for breast cancer." (PMID 25385471, 2015). "Further, B-MYB and FOXM1 target genes, such as CCNB1 and AURKA, are associated with breast cancer." (PMID 25909288, 2015). "Taken together, these results indicate that 3D1 mAb treatment diminishes Nodal expression, as well as downstream phosphorylation of Smad2 and ERK1/2, and reduces Cyclin B1 while increasing p27 in melanoma cells and that similar effects can be observed in breast cancer cells." (PMID 26460952, 2015). "In breast cancers, ZER caused G2/M phase cell cycle arrest associated with downregulation of cyclin B1, Ddk1, Cdc25C, and Cdc25B and Bax/Bak-mediated apoptosis in human breast cancer (MDA-MB-231 and MCF-7) cells and retarded growth of MDA-MB-231 xenografts in vivo." (PMID 25025076, 2014). "miR-379 is expressed in breast cancer, regulating interleukin-11 and Cyclin B1." (PMID 25405349, 2014). "Moreover, treatment of human breast cancer cells with CFM-4 resulted in reduced expression of cyclin B1." (PMID 23826121, 2013). "Dvory-Sobol and colleagues demonstrated that celecoxib induces G2/M arrest associated with cyclin-B1 down-regulation in K-RAS-transformed enterocytes, and in the COX-2 expressing murine breast cancer cell line MCa-35, celecoxib induced a G2/M arrest followed by apoptosis." (PMID 23566419, 2013). "As haplotype and diplotype analysis may provide more power to detect association than single marker analyses alone, we also detected the associations of haplotypes and diplotypes in CCNB1 and CDK1 with breast cancer risk." (PMID 24386390, 2013). "In this study, we hypothesized that the genetic variation in CCNB1 and CDK1 had great impact on susceptibility, progression and survival of breast cancer." (PMID 24386390, 2013). "Similarly, the G2/M checkpoint regulators, cdk1 and cyclin B1, have been shown to be expressed at higher levels in more advanced breast cancer lesions." (PMID 22194735, 2011). "The first reported study of cyclin B1 expression in breast cancer comprised only 73 cancers." (PMID 19293801, 2009). "If verified the results of this study suggest cyclin B1 immunohistochemistry is a method that could easily be adapted for routine use as a prognostic marker in breast cancer." (PMID 19293801, 2009).
breast carcinoma (continued). "Conclusions are, however, in line with the ones suggested by earlier smaller studies, and we feel the role of cyclin B1 as prognostic factor in breast cancer deserves to be further validated, utilising specifically the methods and cut-offs designed in this study." (PMID 19293801, 2009). "We were at first interested whether breast cancer cell lines are similarly sensitive to specific downregulation of cyclin B1 by siRNA." (PMID 19113992, 2008). "Moreover, targeting cyclin B1 sensitizes breast cancer cells to taxol, suggesting that specific cyclin B1 targeting is an attractive strategy for the combination with conventionally used agents in gynecological cancer therapy." (PMID 19113992, 2008). "Interestingly, the combination of cyclin B1 siRNA with taxol substantially enhanced the inhibitory effect on proliferation of breast cancer cells." (PMID 19113992, 2008). "Thus, the combined action of cyclin B1 knockdown together with taxol enhances antiproliferative and proapoptotic responses in breast cancer cells." (PMID 19113992, 2008). "Importantly, siRNA mediated cyclin B1 knockdown in combination with chemotherapeutical agent taxol, enhanced the antiproliferative effect on breast cancer cells." (PMID 19113992, 2008). "In addition, overexpression of cyclin B1 is related to aneuploidy and high proliferation of human mammary carcinomas." (PMID 19113992, 2008). "The data indicate that the combination of reducing cyclin B1 with chemotherapeutic drugs could be a new strategy for molecular intervention in a subset of breast cancers." (PMID 19113992, 2008). "Moreover, overexpression of cyclin B1 is involved in the resistance to radiotherapy in head and neck squamous cell carcinoma and nuclear cyclin B1-positive breast carcinomas are resistant to adjuvant therapy." (PMID 19113992, 2008). "To determine whether this was indeed the case, we tested the primed CTL cultures for the presence of T cells specific for three well known tumor antigens expressed in breast cancers, namely cyclin B1, MUC-1 and survivin." (PMID 17129372, 2006). "The discovery of cyclin B1 as a potential target for T cells in patients with breast as well as head and neck cancers expanded the spectrum of defined tumor antigens expressed in breast cancer." (PMID 17129372, 2006). "In an extension of that work, here we demonstrate that DCs loaded with killed allogeneic breast cancer cells can prime naïve CD8+ T cells to differentiate into tumor antigen specific CTLs by confirming their specificity for three known breast cancer antigens: cyclin B1, MUC-1, and survivin." (PMID 17129372, 2006). "Additionally, FOXM1, an oncogenic transcription factor highly expressed in various cancers—including skin, colon, and breast cancers—induces EMT by modulating key molecules such as cyclin B1, Slug, and Snail, thereby promoting tumor cell proliferation and migration." (PMID 40186131, 2025). "The results of the present study show that autophagy initiated by D-arabinose is accompanied by down-regulation of CDK1 and Cyclin B1 and up-regulation of p21 and p27, suggesting that D-arabinose may modulate autophagy via cell cycle regulators in breast cancer cells." (PMID 38789954, 2024). "Thus, due to its relation with an aggressive phenotype, cyclin B1 might be considered a strong independent prognostic factor in breast cancer." (PMID 33920506, 2021). "For example, in human breast cancer cells, quercetin inhibits lapatinib-sensitive and -resistant breast cancer cell growth by modifying levels of factors that regulate cell cycle G2/M progression and apoptosis, such as cyclin B1, p-Cdc25c (Ser216), Chk1, caspase 3, caspase 7, and PARP." (PMID 27827912, 2016). "Furthermore, upregulation of CCNB1 along with other cell-cycle genes indicates poor survival in various cancers, and upregulation of CCNB1 alone is suggested to be a marker for a poor prognosis in breast cancer, making CCNB1 an interesting target candidate also in GBM." (PMID 21533266, 2011).
breast carcinoma (continued). "Thus, T cells specific for cyclin B1 could be detected after priming and two rounds of boosting with DCs loaded with killed breast cancer cells." (PMID 17129372, 2006). "Cyclin B1 is highly expressed in HCC, breast cancer, bladder cancer, and other cancers, promoting the proliferation and invasion of cancer cells." (PMID 39822992, 2025). "CCNB1 and CCNB2 are frequently overexpressed in breast cancer, especially in the HER2-positive subtype." (PMID 41009526, 2025). "The metastasis-related gene MMP11 and proliferation-related genes BIRC5, MYBL2, MKI67 (Ki67), AURKA (STK15), CCNB1, and ERBB2 (HER2) from the Oncotype DX gene set exhibit significant up-regulation in tumor samples of breast cancer (BRCA)." (PMID 38254834, 2024). "In breast cancer cell lines, the CDK/cyclin B1 complex can increase the phosphorylation level of PBK by inhibiting protein phosphatase alpha-1, thereby promoting mitosis." (PMID 39649886, 2024). "Finally, given that combination therapy caused decreased cyclin B1 expression in AI-resistant cells, this may represent a unique opportunity to expand the repertoire of cell cycle inhibitors that can be purposed for endocrine resistant HER2+ breast cancer." (PMID 37049472, 2023). "This analysis indicates that the mRNA levels of multiple mitotic regulators, including TTK, Nek2, PLK1, Cyclin B1, BUB1, Aurora kinases A and B, and NDC80 (also known as HEC1) are elevated in breast cancers in NHB women." (PMID 36494865, 2022). "The results indicated three CCNB1 isoforms, including CCNB1-001, CCNB1-003, and CCNB1-006, and the isoform PLK1-001 of PLK1, were highly expressed in breast cancer samples." (PMID 35456460, 2022). "Taken together, our study highlights CCNB1 and PLK1 as potential anti-breast cancer drug targets and prognostic markers." (PMID 35456460, 2022). "Further, the significance of Cyclin B1 and CDK1 was highlighted for the first time in context to cell cycle arrest in d-limonene treated breast cancer cells." (PMID 36307489, 2022). "Cyclin B1, cyclin A, and CENPF were overexpressed in several tumor types including esophageal carcinoma, bladder urothelial carcinoma, breast cancer, and colon adenocarcinoma." (PMID 35484963, 2022). "We analyzed the expression levels of their isoforms and found that the expression levels of CCNB1-001, CCNB1-003, CCNB1-006, and PLK1-001 in breast cancer tissues were higher than those in normal tissues." (PMID 35456460, 2022). "We selected the GEPIA2 database to analyze the expression of CCNB1 and PLK1 isoforms in breast cancer patients." (PMID 35456460, 2022). "To further explore the role of CCNB1 and PLK1 in the development of breast cancer, we used the GEPIA2 database to analyze the expression levels of CCNB1 and PLK1 at different clinical stages." (PMID 35456460, 2022). "Ten genes, including CCNB1, CDH1, KDR, RAB25, PRKCA, etc., found which can maintain the high accordance of mRNA–protein for both breast cancer patients and cell lines in basal-like subtypes for the first time." (PMID 36360219, 2022). "That is consistent with previous studies that the knockdown of RIOK1 significantly rewards the protein level of Cyclin B1 and phospho-AKT in breast cancer cells." (PMID 35281872, 2022). "In breast cancer, CCNB1 has a prominent predictive potential for distant metastasis-free survival, DFS, RFS, and OS of breast cancer patients, and it can be a biomarker of prognosis of breast cancer." (PMID 34434217, 2021). "We found that eight cyclins (CCNA2, CCNB1, CCNB2, CCND2, CCNE1, CCNE2, CCNF, CCNO) were differentially expressed between breast cancer and normal tissue samples, with the cut-off criterion of log2(fold change) >1, p < 0.05." (PMID 33791304, 2021). "It should be noted that they also observed that in a cohort of 18 HER2+ breast cancer explants, the effect of T-DM1 paralleled the accumulation of cyclin B1." (PMID 35008318, 2021).
breast carcinoma (continued). "The proteins, cyclin B1, cyclin E1, 4E-BP1, PKC-α, and RAB 25 were highly correlated with mRNA expression in breast cancer." (PMID 33324562, 2020). "There are 81 key genes shared by all stages, among which RPL17, CCNB1, and SF3B4 are genes that are highly (with degrees >25) related to breast cancer." (PMID 32461838, 2020). "Also, a study on breast cancer cells (MDA-MB-231 and MCF-7) showed that Zerumbone could lead to G2/M phase cell cycle arrest associated with Bax/Bak-mediated apoptosis and downregulation of cyclin B1, Ddk1, Cdc25C, and Cdc25B." (PMID 32454937, 2020). "Cyclin B1 and CDC2 were revealed to cooperate positively to play a role in the progression of breast carcinomas, as determined through immunohistochemical (IHC) staining." (PMID 30965609, 2019). "Another antibody array study revealed that cyclin D2, cytokeratin 18, cyclin B1, hnRNP m3-m4 and the monophosphorylated ERK were decreased in a doxorubicin resistant breast cancer cell line in comparison to a sensitive one." (PMID 31014274, 2019). "In conclusion, our results indicate that expression of CCNB1 and CDC6 in breast cancer tissues is higher than in adjacent normal breast tissues." (PMID 31157164, 2019). "We observed that transfection with SALL1 significantly increased the gene expressions of Cyclin A2, Cyclin B1, Cyclin E1, CDK2 and CDK4 in breast cancer MDA cells, which are important for checkpoint regulation in G1-S transition and S phases." (PMID 29625565, 2018). "And moreover, in human breast cancer, miRNA-211 directly inhibit CDC25B expression in breast cancer cells, alters other related target proteins CCNB1 and FOXM1, and then inhibits breast cancer cells growth, migration, and invasion and lead G2/M arrest." (PMID 28924391, 2017). "The correlation between cyclin B1 and MYC gene copy number was also observed in clinical breast cancer samples, supporting the role of MYC in regulating cyclin B1 expression." (PMID 27486754, 2016). "Mechanistically, SL4 induced G2/M arrest in breast cancer cells by activating the MAPK/p21 signaling axis, which subsequently regulated the activity of the CDK1/cyclin A2 and CDK1/cyclin B1 complexes." (PMID 27819344, 2016). "The Kaplan–Meier plots were generated by the mRNA expression levels of Cyclin B1 and CDK1 for OS of breast cancer patients who received adjuvant chemotherapy." (PMID 27486754, 2016). "Further, correlating with the high expression levels of ERLIN2, Cyclin B1 protein levels in human breast cancer cell lines, SUM44, SUM52 and SUM225, were markedly higher than those in the breast cancer cell lines with low ERLIN2 levels ​." (PMID 27462423, 2015). "The CCND1, CCNB1, and STAT1 genes neighboring BRCA1 have also been reported to have important roles in breast cancer recurrence." (PMID 24497942, 2014). "AURKA, BIRC5, CCNB1, MKI67 and MYBL2 are well characterized genes involved in breast cancer proliferation." (PMID 22046260, 2011). "To study the function of cyclin B1 in breast cancer cells we selected cancer cell lines MCF-7, BT-474, SK-BR-3 and MDA-MB-231, as they represent the best characterized cell lines for breast cancer research." (PMID 19113992, 2008). "In breast cancer, there is also evidence that the CDK1/CCNB1/PLK1 axis may be one of the potential pathways by which KIF2C affects tumor progression." (PMID 41333555, 2025).
breast carcinoma (continued). "Some studies have reported the role of CCNB1, CCNB2, PTTG1, RACGAP1, and UBE2C in cell cycle regulation, aggressive tumor behavior, a poor prognosis, resistance to therapy, and cancer stem cell regulation in breast cancer." (PMID 41009526, 2025). "Blocking the CXCL12/CXCR4 pathway may suppress the growth of breast cancer cells by reducing the expression of proteins that facilitate the G2-M phase transition (PLK1, Myt1, and cyclin B1), and then disrupting mitotic processes." (PMID 39703847, 2024). "Importantly, the four most important hub genes RRM2, HMMR, EZH2, and CCNB1 appeared to play a significant role in various types of cancer such as non‐small cell lung carcinoma (NSCLC), liver and breast cancer." (PMID 39118438, 2024). "Furthermore, decreased MUC16 expression results in an accumulation of breast cancer cells at the G2/M phase of the cell cycle via Cyclin B1 and phosphorylation of AURKA, which in turn leads to apoptosis of breast cancer cells through JNK signaling." (PMID 39149564, 2024). "We previously identified CCNB1 as an overexpressed gene in BC with positive LVI using two large transcriptomic cohorts of BC, including the Molecular Taxonomy of Breast Cancer International Consortium (METABRIC) and The Cancer Genome Atlas (TCGA), using artificial neural network (ANN) methodology." (PMID 36418517, 2023). "Previous investigators have found that cyclin CDK1, CCNB1 and CCNA2 are commonly overexpressed in TNBC and correlated with worse OS in breast cancer, so they could act as novel biomarkers for TNBC treatment." (PMID 37667382, 2023). "The disassociation of CDC2/cyclin B1 complex in MDA-MB-231 cells by SFN may occur through the phosphorylation of CDC2 and reduce the CDC2 activity in breast cancer cells." (PMID 37189614, 2023). "Cyclin B1 (CCNB1), which is essential for cell cycle progression through mitosis, is overexpressed in various cancers compared with normal cells and tissues like breast cancer and non-small cell lung cancer." (PMID 36601001, 2022). "The results indicated that CCNB1 and PLK1 expression level in stage III were higher than other stages, suggesting they might play special roles in the development of breast cancer, especially in stage III." (PMID 35456460, 2022). "In addition, the Kaplan–Meier survival analysis of fifteen hub genes demonstrated that the high expression of CCNB1 and PLK1 was significantly correlated with the low survival rate of breast cancer patients." (PMID 35456460, 2022). "Additionally, multiomics studies have revealed CCNB1 and butyrophilins as potential prognostic biomarkers for ACC and breast cancer, respectively." (PMID 36430577, 2022). "The mode of action of eudesmane SLs involves perturbation of MT stability at the levels of both tubulin polymerization and depolymerization, and upregulation of p-Cdk1 (Tyr15) and cyclin B1 in leukemia (CCRF-CEM murine), breast cancer (MCF-7), and hepatoma (HA22T/VGH) cells." (PMID 35651747, 2022). "For example, a multigene assay score that is used to predict recurrence in Breast Cancer has a proliferation (tumor growth) component that is composed of the expression of five genes (Ki67, STK15, Survivin, CCNB1, and MYBL2) combined by averaging the five gene scores." (PMID 34657591, 2021). "Interestingly, some genes involved in these processes and signal pathways, such as CCNB1, CDK1, CHEK2, and MYBL2, have been widely reported as oncogenes and used in the clinical diagnosis for breast cancer patients." (PMID 34646403, 2021). "On the one hand, we found that knockdown of PRMT1 decreased Cyclin E2, Cyclin B1 and CDK4 expression in MCF7 and MDA-MB-231 breast cancer cells; on the other hand, we also confirmed that ectopic expression of PRMT1 increased the expression of these mentioned proteins." (PMID 34775498, 2021).